BMPR1A (bone morphogenetic protein receptor type 1A)
Diseases named in the same sentence as BMPR1A in open-access papers (continued):
Sharing a sentence is not in itself a finding about the gene and the disease.
skeletal dysplasia (2 papers, 2021 to 2026). Any Mendelian diseases that affects growth and development of the skeleton. "Furthermore, a previously reported likely pathogenic BMPR1A variant was found to be shared by normal consanguineous parents who presented for prenatal counseling regarding recurrent skeletal dysplasia and IUFD (20DG1384)." (PMID 34645488, 2021).
colonic polyps (1 paper, 2022). "One patient was diagnosed with CRC at presentation: a 19 years old male with the BMPR1A Bukharin mutation and a high burden of colonic polyps." (PMID 35057835, 2022).
BMPR1A also shares sentences with these, for which no sentence is quoted: Peutz-Jeghers syndrome (7 papers); glioma (4); Lynch syndrome (4); Cowden syndrome (3); iron overload (3); cardiovascular disease (2); congenital heart disease (2); familial colorectal cancer (2); gastric polyposis (2); hamartomatous polyp (2); Hepatic steatosis (2); Infertility (2); iron deficiency (2); melanoma (2); mutyh-associated polyposis (2); pancreatic cancer (2); ventricular septal defect (2); acute kidney injury (1); adenocarcinoma (1); aneurysm (1); ankylosing spondylitis (1); Anophthalmia (1); aortic stenosis (1); ascending colon cancer (1); basal cell carcinoma (1); bladder tumors (1); cholangiocarcinoma (1); chondrodysplasia (1); chronic kidney disease (1); colon adenocarcinoma (1).
A further 49 diseases each share a sentence with BMPR1A in 1 paper.